STAT3 (signal transducer and activator of transcription 3)
Diseases named in the same sentence as STAT3 in open-access papers (continued):
Sharing a sentence is not in itself a finding about the gene and the disease.
tumor (continued). "In sum, our work uncovers a complex role for IL-6 in regulation of tumor immunity: IL-6 induces alternative Mφ polarization and anti-inflammatory immune suppression, whereas it stimulates pro-inflammatory CD40 expression via Stat3/HIF-1α in GBM." (PMID 34103524, 2021). "A STAT3-specific inhibitor, NSC74859, could decrease HCC cells with high RALYL expression in cell proliferation and tumor growth." (PMID 33750796, 2021). "Protein levels of HER signaling pathway members and STAT3 in tumor tissues showed a synergistic decrease in EGFR, HER2 and STAT3, and the activation of HER3 and downstream signaling effectors Akt and ERK was abrogated by joint treatment in both SKBR3 and SKBR3-L xenografts." (PMID 34290605, 2021). "We conclude that the growth promoting and anti-apoptotic mechanisms activated by IL-6, but not IL-6-mediated STAT3 activation, are critically involved in Eμ-myc driven tumor initiation and progression." (PMID 33651821, 2021). "Finally, we established a xenograft model and confirmed that the overexpression of FAM99A inhibits HCC tumor growth, downregulates GLUT1, and blocks nuclear translocation of STAT3 in vivo." (PMID 34765550, 2021). "Thus, strong evidence suggests STAT3 activity is a key modulator of CAF function and their ability to produce and remodel the ECM which helps sculpt an environment permissible to tumor growth and spread." (PMID 34858425, 2021). "We found that STAT3 knockdown in ICC cells or pretreatment of ICC cells with S3I-201 alleviated the protumor effects of TANs and TAMs on those cells in vitro and promoted tumor growth and metastasis in mouse xenografts." (PMID 33692217, 2021). "In tumor-bearing mice, STAT3 inhibition resulted in MDSC depletion in spleens, but not tumors, leading to the notion that the signaling pathways governing these cells and their differential downstream effects are critical in their immunosuppressive capacity." (PMID 33800156, 2021). "Since STAT3 has been shown to be a molecular hub and plays a significant role in GBM tumor progression, we further examined whether knockdown of GSTM1 significantly decreased phosphorylated STAT3 (STAT3-pSer727) levels." (PMID 34732244, 2021). "Previous studies have suggested that JAK2/STAT3 pathway participates in the regulation of angiogenesis, and blockade of the JAK2/STAT3 pathway could inhibit tumor growth." (PMID 33976735, 2021). "STAT3 and STAT5 have been reported to act by inhibiting the antitumor immune response by activating, at least in part, the production of inflammatory cytokines (IL-1, IL-17, IL-10, TGF-β, or VEGF) and promoting tumor growth and metastasis." (PMID 33718197, 2021). "Pharmacologic inhibition of STAT3 via administration of C188-9 also improved the response of NSCLC xenografts to cisplatin and vinblastine, and significantly reduced tumor growth in the combination-treated group compared to mice treated with single agent chemotherapies." (PMID 34944848, 2021). "In addition, we used the adjacent normal tissue to compare with the tumour tissue for the correlation of CREPT and p-STAT3." (PMID 33531691, 2021). "Furthermore, human microglia can promote TMZ resistance by the augmented expression of inflammatory IL-11, which activates the STAT3 (signal transducer and activator of transcription 3)-MYC pathway in tumor cells." (PMID 34646780, 2021). "At the molecular level, Lcn-2 is regulated through the activation of the signal transducer and activator of transcription 3 (STAT3) and CCAAT-enhancer-binding protein (C/EBP) β transcription factors in MΦ in response to the uptake and recycling of apoptotic tumor cells." (PMID 33808732, 2021). "In summary, overexpression of the GSK3β, β-Catenin, STAT3, and CD44 oncogenes and downregulation of the miR-135b tumor suppressor in GBM tumor samples compared to adjacent normal tissue were associated with poor patient prognoses, stemness, and therapeutic resistance." (PMID 33671112, 2021).
tumor (continued). "Under certain treatment scenarios, such as radiation and signal transducer and activator of transcription 3 (STAT3) blockade, dendritic cells are drawn into the TME forming immune activating immune cluster interactions that ultimately result in tumor clearance from the CNS." (PMID 34440802, 2021). "Loss of IL-6 and use of inhibitors of STAT3 and MEK/ERK pathways suppress tumorigenesis in 3D organotypic and tumoroid models, showing how STAT3 and MEK/ERK pathways are also solicited in crosstalk between tumour cells and GCAFs for the maintenance of tumour integrity." (PMID 33810350, 2021). "In addition, Cyr61 promotes vasculogenic mimicry (VM) formation, thereby promoting tumor growth and metastasis through a αVβ5/FAK/HIF‐1α/STAT3/MMP2 signaling cascade." (PMID 33999512, 2021). "Thus, activation of STAT3 in CD4+ T cells generates an inflammatory environment around the OvCa, which promotes tumor growth by stimulating angiogenesis and suppressing anti-tumor response." (PMID 34248988, 2021). "In addition, the G-CSF secreted by tumor cells induced MDSC recruitment and decreased their generation number by using STAT3 inhibitor." (PMID 34527668, 2021). "Therefore, the BRG1/STAT3/VEGFC axis promotes lymphangiogenesis and lymph node metastases in CRC cells and tumor tissues." (PMID 34440220, 2021). "Furthermore, STAT3 has been shown to mediate immunosuppressive effects in the TME via production of IL-10 and TGF-β, supporting tumour growth whilst reducing anti-tumour immunity." (PMID 33546207, 2021). "Although we demonstrated that W2014-S selectively inhibit STAT3 signaling and inhibit tumor growth in vitro and in vivo, without co-crystal information, it is hard to tell where and how this compound interact with STAT3." (PMID 33391507, 2021). "PIVKA-II binds to the hepatocyte growth factor receptor, c-MET, leading to tumour growth, invasion and tumour metastases via the JAK-1/STAT3 and ERK 1/2 MAPK signalling pathways, whereas AFP is thought to be more a marker for hepatic progenitor cells or their subtypes." (PMID 34853657, 2021). "The tumor-promoting role of these cells has been demonstrated by Treg-specific deletion of RORγt in CAC mice, which resulted in decreased tumor incidence and decreased expression of ki67 and STAT3 in dysplastic lesions." (PMID 34884543, 2021). "In summary, complicated STAT3/NF-κB crosstalk is established between CSCs and TAMs in the TME, in which CSCs attract, re-educate, and put macrophages into their service to support primary tumor growth." (PMID 34235155, 2021). "Moreover, although it did not significantly affect the level of TNF‐α and IL‐6 in liver tissues, S3I‐201 obviously restrained the enhanced STAT3 activation and EMT change of tumour tissues in the liver injury group." (PMID 33410581, 2021). "Here, we hypothesized that the activated STAT3 was translocated to the nucleus and bound to the MMP2 promoter to stimulate tumor cell invasion, and was bound to the PD-L1 promoter to boost tumor metastasis or regulate immune escape." (PMID 33805840, 2021). "Onion A, a sulfur compound from onion, exhibited antitumor effects by inhibiting the activation of suppressing signal transducer and activator of transcription-3 (STAT3) in myeloid lineage cells, and impaired the development of subcutaneous tumor and lung metastasis in tumor-bearing mice." (PMID 34368207, 2021). "Moreover, the Western blot results showed GLA significantly reduced p-STAT3 expression and increased cleaved PARP and cleaved caspase-3 in tumor tissues compared with the control group." (PMID 34923957, 2021). "Regarding potential mechanisms, leptin can activate the JAK2/STAT3, PI3K/Akt/mTOR, and extracellular regulated protein kinase (ERK) pathways by binding to its own receptors expressed in tumor cells and stromal components, including immune cells, endothelial cells and tumor-associated fibroblasts." (PMID 33842335, 2021).
tumor (continued). "STAT3, an important member of the JAK/STAT signaling pathway, is negatively regulated or activated by PLK1, leading to the up-regulation of the downstream gene MMP2, thereby enhancing the aggressiveness of tumor cells." (PMID 34858165, 2021). "Decreased levels of FAO were observed after STAT3 inhibition, while supplementation with the medium‐chain FA (myristic acid), which can bypass the need for CPT1B, reversed the inhibition of tumor spheroid formation and drug resistance induced by JAK/STAT3 inhibition." (PMID 34766135, 2021). "Recently, numerous studies have substantiated that both STAT3 and the EMT are closely related to the initiation and development of malignant tumours, and the STAT3 protein has the potential to become an ideal drug target for anti-tumour therapy." (PMID 33546665, 2021). "Prior accounts utilizing Salmonella as a delivery vector for RNA interference targeting the expression of oncogenic products, including STAT3, Bcl-2, P-glycoprotein, and HIF-1, has been demonstrated to promote significant tumor regression and increased survival in murine models." (PMID 34829795, 2021). "Furthermore, we investigated the correlation between TRAIL and PD-L1 and found that TRAIL upregulates PD-L1 expression through the STAT3/ERK signaling pathway, further inducing EMT and tumor progression in ESCC." (PMID 34167551, 2021). "In summary, we identified MB49-derived exosomal miRNAs could induce macrophage polarization to immunosuppressive phenotype by activating PTEN/AKT/STAT3/6 pathways, thus contributing to the establishment of immunosuppressive TME to facilitate tumor growth." (PMID 34521440, 2021). "Since circFat1 KD attenuated STAT3 activation and SOX2 expression, we further examined whether circFat1 KD could enhance PD1 blockade‐mediated immunotherapy of HNSCC by activating tumor cell intrinsic type 1 IFN signaling." (PMID 34258151, 2021). "Our results showed that in all six patients, p-STAT3 in αSMA+ CAFs were only detectable in tumor sections post-PARPi treatment, but not in patient-matched biopsies taken before PARPi therapy." (PMID 34956861, 2021). "Therefore, we analyzed the same patient tumor samples for CAF marker αSMA (alpha-smooth muscle actin) expression and p-STAT3." (PMID 34956861, 2021). "As one homologue of STAT3, STAT1 usually functions as a tumour suppressor." (PMID 33546665, 2021). "In the present study, we identified the frequencies of genetic alterations of STAT3/CDK2/4/6 in multiple cancer types, identified the gene signature as oncogenic prognosticators of CAFs and tumor immune infiltration, and poor prognoses of clinical cancer cohorts." (PMID 33668805, 2021). "Indeed, within the tumor microenvironment, IL-6 secreted by TNBC cells upregulates CCL5 expression in lymphatic endothelial cells by activating the IL-6 receptor, STAT3, which subsequently enhances transcription of the CCL5 gene." (PMID 34445170, 2021). "It is reported that IL-8 secreted by tumor-infiltrating macrophages may promote the EMT and invasiveness of cancer cells by activating the JAK2/STAT3 signaling pathway." (PMID 34867344, 2021). "IL-11 stimulation-induced STAT3 phosphorylation in AKTP tumor organoids and human tumor cell lines, prompting us to compare the signals induced by IL-11 in normal colon and tumor organoids." (PMID 33863879, 2021). "Genes of the STAT3 pathway and of the STAT3 activator IL6 are significantly enriched in group PF_EPN_A, suggesting the establishment of a feedforward loop between tumor cells and the inflammatory microenvironment, which can provide additional druggable vulnerabilities by BETi in EPN." (PMID 33668642, 2021). "Although STAT3 is a key modulator for PD-L2 and FASL in tumor cells, it remains unclear if STAT3 is the key transcription factor that modulates PD-L2 and FASL expression in CAFs." (PMID 34858425, 2021).
tumor (continued). "The JAK-STAT pathway is also involved in the genesis, progression, metastasis and drug resistance of tumors, especially STAT3 and STAT5 can continuously activate the survival, proliferation and invasion of tumor cells, which are of great interest in cancer biology." (PMID 34135756, 2021). "STAT3 inhibition might thus have consequences in shaping TME towards anti-tumor phenotype by acting on both immune and tumor cells." (PMID 34138876, 2021). "More specifically, tumor cells adhere to stromal cells, activate several antiapoptotic pathways such as Janus kinase (JAK)/signal transducer and activator of transcription 3 (STAT3) and upregulate anti-apoptotic proteins such as BcL-xL, nuclear factor-κB (NF-κB) and Mcl-1." (PMID 34768861, 2021). "Tumor weight from mice of the two experiment groups (STAT3-NC + AETW, STAT3-OE + AETW)." (PMID 34867344, 2021). "We conclude that the growth-promoting and anti-apoptotic mechanisms activated by IL-6 are critically involved in Eμ-myc driven tumor initiation and progression, but the B cell intrinsic expression of STAT3 is not required." (PMID 33651821, 2021). "In such a way, STAT3 and HIF-1α can mediate tumor immunity and immune evasion." (PMID 34692527, 2021). "IL-6 activated STAT3 and NF-kB/TIM4 signals to regulate tumor progression." (PMID 34657635, 2021). "The STAT3 signaling pathway is activated by STAT phosphorylation, which increases the expression levels of target genes, such as vascular endothelial growth factor (VEGF), in all tumor growth processes." (PMID 34129726, 2021). "The inhibition of STAT3 prevented L1CAM-dependent OC stemness and tumor initiation." (PMID 34645505, 2021). "Moreover, STAT3 signalling and mTOR signalling in lymphatic endothelial cells (LECs) within the PMN facilitate tumour cell extravasation and colonization." (PMID 35006432, 2021). "Similarly, the TKI-mediated STAT3 activation is the basis of chemoresistance in HER, MET, and ALK tumor models." (PMID 33431808, 2021). "Thereby, leading to the question, if miRNAs such as miR-14b or the miR-200 family of miRNAs were to be up-regulated could they then target genes that are overexpressed or active like STAT3 and EMT inducers to inhibit tumor growth?" (PMID 34350123, 2021). "For example, CUR through suppression of EMT, angiogenesis, and STAT3 and NF-ĸB signaling, modulation of the expression of tumor-related-ncRNA, apoptosis stimulation, AMPK activation, inhibition of STAT3 and NF-ĸB signaling, and induction of autophagy can affect OCa." (PMID 34959716, 2021). "Interestingly, HIF-1α has been found to both inhibit proapoptotic proteins, including TRAIL, and activate anti-apoptotic proteins, such as survivin, c-myc, STAT3, and TCF4, to promote the survival of tumor cells under chemo- or radio- therapies." (PMID 33732706, 2021). "IL-8 acts through AKT, MAPK, STAT-3 intracellular pathways, ERK extracellular pathway and SNAIL, which is a signal that leads to conversion from epithelial to mesenchymal cells necessary for tumor progression." (PMID 34944856, 2021). "Meanwhile, it could not only accelerate the tumor growth but also promote the EMT and upregulate the expressions of active forms of JAK and STAT3." (PMID 34867344, 2021). "Downregulation of KCNQ1OT1 inhibits SCLC cell proliferation, migration, and invasion, induces apoptosis, and suppresses tumor growth and chemoresistance via TGF-β-mediated EMT signaling and the Janus kinase (JAK)/signal transducer and activator of transcription 3 (STAT3) signaling pathway." (PMID 34827600, 2021). "Resveratrol (RV), a polyphenol in grapes, is known to be a potential noncytotoxic tumor-preventive drug targeting STAT3 signaling." (PMID 33762015, 2021). "Furthermore, combined inhibition of STAT3 (by ruxolitinib) and ERK1/2 (by trametinib) sensitized NB cells to etoposide and led to decreased tumor size and prolonged survival of mice." (PMID 33287630, 2021).
tumor (continued). "Disruption of the TGF-β/KIT signaling loop on the level of the SCF/STAT3 axis restores TGF-β tumor suppressor function by inhibition of epithelial-mesenchymal transition (EMT), tumor cell migration, and invasion, and restoration of its cell cycle inhibitory functions." (PMID 33603771, 2021). "Upstream regulator prediction revealed IL-6 identified as the top upstream regulator in the fat of KPC tumor mice; neither IL-6 nor STAT3 was discovered among upstream regulators in adipose of mice with KPC IL6KO tumors." (PMID 33851955, 2021). "Intriguingly, p-STAT3 levels from bulk PDAC tumor samples do not significantly change between WT and IL-6 KO mice, nor in response to doxorubicin treatment at the times examined." (PMID 34711820, 2021). "Using targeted small molecule inhibitors, Ref‐1 redox signalling was blocked along with STAT3 activation, and tumour growth evaluated in the presence and absence of the relevant tumour microenvironment." (PMID 33274592, 2021). "Compared with the control group, the xenograft tumours from mice treated with CVB exhibited an evident decrease in the levels of IGFBP3, p-AKT, p-STAT3, p-ERK, p-JNK, p-P38, Bcl-2, Snail, and Vimentin, while the levels of cleaved Caspase 3 and E-cadherin were increased." (PMID 34512163, 2021). "Notably, the tumor suppression rate was -52.65%, suggesting the effect of AETW was counteracted by the addition of overexpressed STAT3." (PMID 34867344, 2021). "First, we found that mouse bodyweight in the anti-PD-1 treatment group increased during tumor progression, while STAT3 downregulation did not alter the weight." (PMID 33936081, 2021). "Also, SHP099 and AMG386, individually or together increased significantly p‐STAT3 and p‐ERK1/2 levels in tumor CD31+ endothelial cells (and EV5F)." (PMID 34102002, 2021). "The nuclear localisation of STAT3 and STAT5B observed in EATL type I, type II and PTCL-NOS tumour cells prompted us to analyse whether this is a recurrent phenomenon." (PMID 34680385, 2021). "Moreover, S. mansoni soluble egg antigens activate c-Jun (proto-oncogene) and STAT3 (transcription factor), which facilitate the development and progression of HCC tumor formation." (PMID 34956157, 2021). "TKO-mediated activation of STAT3 and/or STAT5 regulates expression of common as well as specific genes involved in hematopoietic cell survival, proliferation, metabolism, hypoxia, autophagy, migration and tumor immune evasion." (PMID 31963765, 2020). "Moreover, several lines of evidence showed that STAT3 signaling indeed plays essential roles in the malignant progression of NSCLC and also the other types of tumor 31-32." (PMID 32104503, 2020). "Overall, our findings support a model wherein Th17 cells inhibit the expression of CXCR3 on CD8+ T cells in blood circulation by secreting IL-17A, which activates STAT3 signaling and downregulates CD8+ T cell infiltration in tumor tissues; these effects can be attenuated via Stattic." (PMID 32503584, 2020). "Indeed, tumor-cells enriched from the ascites of EOC patients displayed constitutively tyrosine-phosphorylated forms of STAT1 and STAT3, and also constitutive GBP1 expression." (PMID 32093058, 2020). "STAT3 is broadly hyperactivated both in cancer and non-cancerous cells within the tumor ecosystem and plays important roles in inhibiting the expression of crucial immune activation regulators and promoting the production of immunosuppressive factors." (PMID 32972405, 2020). "In tumor development, visfatin may enhance metastasis and angiogenesis through PI3K/Akt, MAPK, and c-Abl/STAT3 signaling pathways in macrophages, endothelial cells, and breast cancer cells." (PMID 33256011, 2020). "Previous work showed that PTEN deletion affects levels of CK2 through transcriptional STAT3‐mediated upregulation, suggesting that this protein may have an important role in PTEN‐null tumor cells." (PMID 32672423, 2020).